CD4 (CD4 molecule)
Diseases named in the same sentence as CD4 in open-access papers (continued):
Sharing a sentence is not in itself a finding about the gene and the disease.
HIV-1 infection (continued). "These regions are located in mucosal areas of rapid cellular turnover, have a single layer of columnar epithelium, and are populated with a high density of target CD4+ cells, collectively providing evidence that the cervix is the primary site for initial HIV-1 infection." (PMID 27025760, 2014). "Taken together, these results suggest that changes in CD4 cell numbers during HIV-1 infection are a complex summation of proliferating, but mostly short-lived, CD4 T cells, loss of virally infected cells, changes in trafficking, and feedback regulation to limit responses." (PMID 25610441, 2014). "Subsequently, SAMHD1 was shown to restrict HIV-1 infection in resting CD4+ T cells." (PMID 24599229, 2014). "Infection of MT-4 cells by VSV-G pseudotyped MSCV encoding GFP, was not affected by pre-incubation with CD4+ exossomes at concentrations that were inhibitory for Env-dependent HIV-1 infection." (PMID 25423108, 2014). "On the other hand, we observed some evidence for the possible role of non-specific IFN-γ-secreting CD4+ T cells in explaining the vaccine-associated increased risk of HIV-1 infection in Step." (PMID 25369172, 2014). "Importantly, CD4-depleted exosomes released by CD4+ T cells expressing Nef have a reduced capacity to inhibit HIV-1 infection in vitro." (PMID 25423108, 2014). "We previously reported that commensal E. coli exposure augmented HIV-1 infection of LPMCs, but the impact of E. coli exposure on LP CD4+ T cell death remained unknown." (PMID 24495380, 2014). "In contrast, the inflammatory response may increase the number of activated CD4+ T cells and macrophages at the site of HIV-1 infection, leading to more rapid dissemination of the virus by “adding fuel to the fire”." (PMID 24587225, 2014). "Indeed, when examining the percentages of Ig+ CD4+ T cells at different stages of HIV-1 infection, approximately 70% of peripheral resting CD4+ T cells (rCD4s) were coated with surface VRs bound to slow-turnover gp120-Ig." (PMID 24516533, 2014). "We demonstrate that these stable/unstable phenotypes are an intrinsic property of endogenous APOBEC3H proteins in primary CD4+ T lymphocytes and confer differential resistance to HIV-1 infection in a manner that depends on natural variation in the Vif protein of the infecting virus." (PMID 25411794, 2014). "Furthermore, CD4 T cells from “Elite controllers” have been shown to resist HIV-1 infection, reverse-transcribing viral genomes, and transcribing mRNA from proviral DNA less effectively than CD4 T cells from chronically infected HIV-1+ individuals." (PMID 23459797, 2013). "HIV-1 infection requires CD4 expression, which functions as its main receptor." (PMID 23951090, 2013). "The present study investigated the effects of TFV with respect to its ability to modulate 5’-nucleotidase gene expression, nucleotidase biological activity and chemokine production by CD4+ T cells, macrophages and DCs, the main target cells for HIV-1 infection." (PMID 24205323, 2013). "In an attempt to compare the ability of DCs once treated with PAMPs to sensitize autologous CD4+ T cells that are resting before initiation of the co-culture to productive HIV-1 infection, we first measured the presence of activation markers on the surface of CD4+ T cells." (PMID 23844079, 2013). "We then examined the capacity of CD8+ T cells from the PTCs to suppress ex vivo the HIV-1 infection of autologous CD4+ T cells, as we recently showed that this test distinguishes the effective CD8+ T-cell responses found in many HICs from the ineffective responses in other patients." (PMID 23516360, 2013). "In the 1990s, we and several others demonstrated that DC are easily susceptible to human immunodeficiency virus type 1 (HIV-1) infection and can therefore also efficiently transmit virus to antigen-specific CD4+ T cells, in spite of low levels of virus production." (PMID 23847602, 2013).
HIV-1 infection (continued). "Moreover, we show that these PAMP-treated DCs promote cis-infection of autologus CD4+ T cells by establishing an intracellular milieu more permissive to productive HIV-1 infection." (PMID 23844079, 2013). "Interestingly, a recent work has shown that a physical contact between DCs and CD4+ T cells is adequate to reduce SAMHD1 activity and allow HIV-1 infection of resting CD4+ T cells." (PMID 23844079, 2013). "Moreover, it has been suggested that a high CXCR4 density on the surface of CD4+ T cells during the course of HIV-1 infection favors the emergence of X4 virus isolates." (PMID 23844079, 2013). "Now that IL-27 has shown potent anti-HIV properties in three important cell types in HIV-1 infection (CD4+ T cell, macrophage and DC), the question remains whether this cytokine may be able to be utilized in the clinical setting." (PMID 23527130, 2013). "This might partially result from a reduced ability of D-zymosan-treated DCs to properly sensitize CD4+ T cells to productive HIV-1 infection." (PMID 23844079, 2013). "It is also important to point out that our HVL group has very low CD4+ T cell count (<200 cells), suggesting that the differentially regulated miRNAs could be the result of non CD4+ T cell types in response to HIV-1 infection." (PMID 23721325, 2013). "Additionally, we showed that stimulation of NK cells with exogenous S100A9 enhances the control of HIV-1 infection in CD4+ T cells." (PMID 24156302, 2013). "To evaluate hNOJ mice as an experimental animal model of HIV-1 infection, we first investigated how the degree of reconstitution affects the cellularity and development of CD4+ T cells using hNOJ (IR+) and (IR−) mice, which represent high and low chimerism groups, respectively." (PMID 23301078, 2013). "CD4+ memory T cells support higher levels of HIV replication than naïve CD4+ T cells, but the mechanism underlying the different susceptibility to HIV-1 infection remains unclear." (PMID 24244453, 2013). "In spite of their structural relatedness, our results indicate that PIM6 is unique among mycobacterial mannosylated glycolipids in its ability to increase HIV-1 infection in primary CD4+ T cells and this is at least partially related to its ability to engage and signal via TLR2." (PMID 24282561, 2013). "Also in case of HIV-1 infection molecules of the B7 family are found to participate in CD4 T cell regulation, in particular PD-1, CTLA-4, and Tim-3." (PMID 23717308, 2013). "As CCR5 expression increases permissiveness to HIV-1 infection 11, the elevated expression of CCR5 on CD4+ BAL T cells might increase BALMC susceptibility to HIV-1 infection." (PMID 23147374, 2013). "HIV-1 infection results in differential regulation of specific cellular genes in target cells such as CD4+ T cells and monocytes/macrophages suggesting that virus infection alters host cellular proteins either to evade the immune system and/or for optimal viral replication." (PMID 23721325, 2013). "By contrast, PIM6 significantly increased productive HIV-1 infection in CD4+ T cells." (PMID 24282561, 2013). "In addition to the apoptosis directly induced by Vpr, accumulating evidence has suggested a role for innate immune activation, including NK cells, in the CD4+ T cell depletion after primary HIV-1 infection in individuals." (PMID 24339781, 2013). "Although the level of immune activation in the early stages of HIV-1 infection is predictive of disease outcome, the kinetics of Type I IFN production in relation to CD4+ T cell loss and viral control over time is largely unknown." (PMID 24130482, 2013). "Indeed, a new, potential aspect of trans infection of CD4+ T cells that should be explored involves its role in the quest for a true or functional cure of HIV-1 infection." (PMID 24278768, 2013).
HIV-1 infection (continued). "A crucial point to understand how HIV-1 changes miRNA cellular milieu is to define the differences between cells prone to HIV-1 infection, that is, activated CD4+ T cells, and cells that are less liable to this infection, that is, resting CD4+ T cells and monocytes." (PMID 23841087, 2013). "Direct HIV-1 infection of HLA-G+ CD4 Treg may contribute to the reduction of these cells in progressive HIV-1 infection." (PMID 23382678, 2013). "Interestingly, a higher restriction in HIV-1 infection was achieved by engrafting mice with transduced CD4+ T cells than with transduced CD34+ HSC cells." (PMID 24167505, 2013). "Further depletion of these immune cells occurs in GALT inductor sites (i.e. Peyer's patches and mucosal lymphoid follicles) as result of chronic HIV-1 infection and persistent mucosal antigenic activation of latently infected cells, such as CD4+ CCR5+ lymphocytes and macrophages." (PMID 24146801, 2013). "Interestingly, BST-2/tetherin up-regulation was recently proposed to occur in most immune cells from patients in the acute phase of HIV-1 infection as well as in simian CD4+ T cells upon SIV infection." (PMID 23311681, 2013). "The functional relevance of GPN-specific CD8+ T cell response or Env-specific CD4+ T cell response in the efficacy of vaccination for prevention of HIV-1 infection remains unknown." (PMID 23826170, 2013). "However, the role of DCIR in trans infection is complicated by findings that DCIR expression is induced in CD4+ T cells by HIV-1 infection and that this is also evident as a paracrine-like effect in uninfected CD4+ T cells." (PMID 24278768, 2013). "As HIV-1 infection induces a down regulation of CD4 expression, we studied the p24 expression in CD3+ T cells as a measure of viral replication; cells were cultured at a NK/CD4 T cell ratio of 1:5, which is close to physiological conditions, without any NK cell cytokine activation." (PMID 24156302, 2013). "In addition, others have demonstrated that TLR2 engagement enhances HIV-1 infection in primary CD4+ T cells." (PMID 24282561, 2013). "Therefore, the activation and subsequent HIV-1 infection of CD4+ T cell cultured with SEA and α-CD3 depends on the presence of an APC, in this case mDC, which provides MHC or costimulatory signaling." (PMID 23590845, 2013). "Together, this shows that the role of HS in mediating in cis HIV-1 infection may depend on the cell surface CD4/HS ratio and their level of regulation." (PMID 24312095, 2013). "Here, we show that non-classical HLA-G-expressing CD4 Treg are highly susceptible to HIV-1 infection and significantly reduced in persons with progressive HIV-1 disease courses." (PMID 23382678, 2013). "Latent HIV-1 infection of resting CD4+ T cells remains the major barrier to HIV-1 eradication." (PMID 23737751, 2013). "In this paper, we introduce fractional-order into a model of HIV-1 infection of CD4+ T cells." (PMID 22214194, 2012). "Since CD4+ T cells serve as primary targets for HIV-1 infection and replication, in this study we have examined whether cocaine enhances HIV-1 replication in CD4+ T cells." (PMID 23251514, 2012). "Next, we assessed whether a transformed T-cell line, such as CD4+ HuT/CCR5 cells, would still require the presence of Vpr to establish a robust single-cycle HIV-1 infection as observed with PBMCs and primary CD4+ T-cells." (PMID 22570689, 2012). "These variants were all associated with IU HIV-1 infection and yet the promoter variants reduced DC-SIGN expression in Hofbauer cells whereas the exon 4 mutations enhanced capture and transmission of HIV-1 to CD4+ T lymphocytes." (PMID 22808239, 2012). "Recent studies also revealed that SAMHD1 restricts HIV-1 infection in resting CD4+ T-cells." (PMID 23231760, 2012). "Furthermore, Vpx increases HIV-1 infection of all resting CD4+ T-cell subsets (naïve, central memory and effector memory cells) by approximately 8- to 15-fold." (PMID 23092163, 2012).
HIV-1 infection (continued). "Two recent studies revealed that SAMHD1 restricts HIV-1 infection in resting CD4+ T-cells, suggesting a common mechanism of HIV-1 restriction in non-cycling cells that may contribute to viral immunopathogenesis." (PMID 23092163, 2012). "Others have observed that HIV-1 infection inhibits autophagy in the MOLT-4 CD4+ T cell line." (PMID 22606989, 2012). "Though a range of hematopoietic cells, including monocyte-macrophages, B lymphocytes, eosinophils, and dendritic cells, as well as columnar epithelial cells, have been found to be infected by HIV-1, the CD4-positive helper T lymphocyte has been identified as the primary target for HIV-1 infection." (PMID 22848825, 2012). "However, this notion is somewhat unsettled because another group has reported that autophagy is induced by HIV-1 infection of CD4+ T cells, as shown by increased levels of Beclin-1 and LC3." (PMID 23110561, 2012). "Even worse, sCD4 at low concentration can enhance HIV-1 infection of CD4-/CCR5+ cells." (PMID 23217195, 2012). "To avoid the exclusion of CD4 T cells that may have down-regulated CD4 expression as a result of HIV-1 infection, we defined CD4 T cells as CD8−CD3+ cells." (PMID 23236398, 2012). "Furthermore, silencing SAMHD1 expression in post-activated resting CD4+ T-cells using specific siRNA or shRNA significantly increases HIV-1 infection, further suggesting that SAMHD1 suppresses HIV-1 infection in post-activated resting CD4+ T-cells." (PMID 23092163, 2012). "Recently, it was reported that minocycline, a second-generation tetracycline derivative, could attenuate HIV-1 infection and replication by suppressing the activation of CD4+ T cells." (PMID 22905236, 2012). "The dysregulation of autophagy by viral proteins, perhaps due to Env-mediated effects on bystander CD4+ T regulatory cells, could contribute to aspects of autoimmunity observed in HIV-1 infection." (PMID 22606989, 2012). "In addition, the frequency of Th1/2 EM and effector subsets among human CD4+ T cells for the infected mice gradually increased after the HIV-1 infection and was significantly higher at 6 weeks post-infection than that for the uninfected ones." (PMID 22880104, 2012). "We then investigated whether the effect of Nef on HIV-1 infection of resting CD4+ T cells correlated with Nef-dependent T-cell proliferation." (PMID 22479639, 2012). "Anaerobic and other bacteria increased in male partners of women with BV may cause inflammation by activating Langerhans cells and CD4+ T-cells, thereby increasing target cells for HIV-1 and susceptibility to HIV-1 infection." (PMID 22745608, 2012). "CD4+ T cells isolated from this group of patients showed increased expression of the cyclin-dependent kinase inhibitor p21 relative to uninfected individuals and individuals with progressive HIV-1 infection." (PMID 24832049, 2012). "Markers of disease severity in HIV-1 infection include CD4+ T cell count and viral load." (PMID 23152825, 2012). "HIV-1 infection of nurse macrophages led to a decline in CD4+ T-cell production." (PMID 22911696, 2012). "Therefore, CB2 activation reduces CXCR4-tropic HIV-1 infection in primary CD4+ T cells in a dose-dependent and receptor-specific fashion." (PMID 22448282, 2012). "Interestingly, the Leu3a-binding site maps to a region within the D1–D2 domain of CD4 that is directly involved in gp120 binding and inhibits gp120 binding and HIV-1 infection in vitro." (PMID 23028850, 2012). "In addition, intrinsic characteristics of the mucosal compartment, including the predominance of activated and well differentiated gastrointestinal (GI) mucosal CD4+ T cells with a memory phenotype permit HIV-1 infection and accommodate its replication." (PMID 22319447, 2012).
HIV-1 infection (continued). "As with the data regarding HIV-1 infection and CD4 T cell depletion we first compared activation of T cells by their expression of CD25, CD38, and HLA-DR in donor-matched tissues infected with a T/F HIV-1 construct, NL-1051.TD12.ecto and a control C/R HIV-1 variant, NL-SF162.ecto." (PMID 23236398, 2012). "Inadequate dietary intake could contribute to the severity of HIV-1 infection and to the depletion of CD4+ T-cell population in addition to the oxidative stress that might arise from depletion of antioxidant molecules." (PMID 22997571, 2012). "Thus, the DC-SIGN neck region variants associated with IU HIV-1 infection enhanced both the capture of HIV-1 by DC-SIGN and its subsequent transmission to the CD4+ T lymphocytes." (PMID 22808239, 2012). "However, depleted CD4+ T cells are replenished because of the regenerative capacity of the immune system and are prone to HIV-1 infection due to the generalized state of immune activation." (PMID 23035819, 2012). "Our data also show that HD5 inhibits HIV-1 infection in primary CD4+ T lymphocytes at concentrations similar to those measured in the female and male lower genital tracts, suggesting that HD5 can function as a natural immune barrier against HIV-1 sexual transmission." (PMID 23028850, 2012). "Moreover, VLP-Vpx treatment of SAMHD1-deficient resting CD4+ T-cells cannot further enhance HIV-1 infection, indicating that SAMHD1 is necessary for Vpx to relieve HIV-1 restriction in resting CD4+ T-cells." (PMID 23092163, 2012). "In summary, cell-associated virus load in breastmilk is a stronger predictor of the risk of early postnatal HIV-1 infection than cell-free virus loads, independent of antenatal CD4 cell count and plasma viral loads." (PMID 23284701, 2012). "In the setting of HIV-1 infection it might be expected that pathogen specific CD4+ cells would be activated by malarial infection and, thus, would be likely to be especially vulnerable to HIV-1 infection." (PMID 22745697, 2012). "There is a broad consensus that macrophages resist HIV-1 infection much better than CD4+ T cells." (PMID 23035819, 2012). "Further investigation into the exact mechanism linking cell cycle arrest to cytopathicity could provide possible targets for therapies that would reduce the depletion of CD4+ T cells during HIV-1 infection." (PMID 21949789, 2011). "CD4+ Th17 cells have been specifically identified as a sensitive, early target for HIV-1 infection." (PMID 22292110, 2011). "It is highly vulnerable to HIV-1 infection, related to the subjacent lamina propria which, in health, is densely populated with activated memory T-cells expressing both CD4 and both HIV-1 co-receptors CCR5 and CXCR4, as well as dendritic cells (DCs) and macrophages." (PMID 21969851, 2011). "Indeed, initial HIV-1 infection of older individuals is likely to be met with a diminished CD4+ T-cell response, which, in turn, would affect both B- and T-cell responses to HIV-1, allowing the virus to spread quickly." (PMID 21298072, 2011). "We, and others, have reported an HIV-1-driven expansion of Treg expression in chronic and acute HIV-1 infection, including a relationship between the expansion of Treg, the level of cellular immune activation and the depletion of CD4+ T cells in acute HIV infection." (PMID 21750674, 2011). "This study indicates that cathepsin B inhibits CD4-independent HIV-1 infection." (PMID 21541353, 2011). "Since we determined that HIV-1 infection has detrimental effects on the absolute numbers of both naïve CD4+ T-cell subsets, we evaluated whether ART was able to restore these subsets to age-appropriate levels." (PMID 21298072, 2011). "Nevertheless, CD4 and CCR5 concentration requirements for R5 HIV-1 infections in vitro have been shown to be interdependent, with viruses being highly dependent on the CD4 concentrations or strength of the initial virus-CD4 bond when cell surface CCR5 density is low." (PMID 21760891, 2011).